LRP8 (LDL receptor related protein 8)
Diseases named in the same sentence as LRP8 in open-access papers (continued):
Sharing a sentence is not in itself a finding about the gene and the disease.
liver fibrosis (1 paper, 2015). "Similarly, in a mouse model of carbon tetrachloride (CCl4)-induced liver fibrosis, miR-130/301 was increased and Pparγ and Lrp8 were correspondingly decreased, accompanied by a positive correlation among collagen crosslinking, miR-130a expression, and YAP nuclear localization." (PMID 26667495, 2015).
lung adenocarcinoma (1 paper, 2022). A carcinoma that arises from the lung and is characterized by the presence of malignant glandular epithelial cells. "The expression of LRP8 in the two most prevalent types of NSCLC, lung adenocarcinoma (LUAD) and lung squamous cell carcinoma (LUSC), and adjacent normal lung tissues were evaluated by bioinformatics analysis." (PMID 35246020, 2022).
metastasis (1 paper, 2025). The spread or migration of cancer cells from one part of the body (where they first appeared) to another. "Our findings revealed that LRP8, an apolipoprotein E receptor, is upregulated in BC patients with brain metastasis." (PMID 40506610, 2025).
metastatic cancer (1 paper, 2025). A carcinoma which has spread from the original site of growth to another anatomic site. "We also successfully isolated brain-colonizing metastatic cancer cell populations, analyzed mRNA expression levels of LRP8 in BM6 and BM0 cells, and conducted RNA sequencing." (PMID 40506610, 2025).
neuropathy (1 paper, 2024). A disorder affecting the nervous system that manifests with pain, tingling, numbness, and/or muscle weakness. "In summary, our study identified compound heterozygous variations that expand the spectrum of pathogenic ACO2 variants and revealed key mediating molecules, LRP8 and ANK3, between ACO2 mutations and the development of neuropathy." (PMID 39600307, 2024).
non-small cell lung carcinoma (1 paper, 2022). A group of at least three distinct histological types of lung cancer, including non-small cell squamous cell carcinoma, adenocarcinoma, and large cell carcinoma. "However, the exact mechanism by which LRP8 exerts its oncogenic role in non-small cell lung cancer (NSCLC) remains elusive." (PMID 35246020, 2022).
pulmonary fibrosis (1 paper, 2015). Chronic progressive interstitial lung disorder characterized by the replacement of the lung tissue by connective tissue, leading to progressive dyspnea, respiratory failure, or right heart failure. "Furthermore, consistent with the direct down-regulation of the associated factors peroxisome proliferator-activated receptor gamma (PPARγ), apolipoprotein E (APOE) and the apolipoprotein E receptor LRP8 by miR-130/301 in PH 9, both Pparγ and Lrp8 were decreased in pulmonary fibrosis." (PMID 26667495, 2015).
cancer (26 papers, 2013 to 2026). A tumor composed of atypical neoplastic, often pleomorphic cells that invade other tissues. "Low‐density lipoprotein receptor‐related protein 8 (LRP8) is a crucial regulator of lipid metabolism and is implicated in the development and treatment of various cancers." (PMID 40372166, 2025). "Additionally, we found that Spon1 loss in the host, or Lrp8 loss in cancer cells, resulted in a significant decrease of both high-density collagen matrices and metastases." (PMID 38716730, 2024). "Generally, this evidence demonstrates the potential impact of LRP8 on the expression of GPX4 in cancer and immune cells." (PMID 41139700, 2026). "LRP8 modulates cancer ferroptosis by regulating selenocysteine levels, which are required for translation of the selenoprotein GPX4." (PMID 41139700, 2026). "Focusing on TNBC cells, we observed that OST-01 downregulated LRP8 (ApoER2), a key regulator of ferroptosis—a process crucial for cancer cell survival, characterized by lipid peroxidation, elevated malondialdehyde (MDA), and decreased GPX4 activity." (PMID 39920848, 2025). "LRP8 promotes cancer cell motility by activating CDC42, a protein that stimulates filopodia formation, enabling cells to “crawl” through the cerebral vasculatures." (PMID 40506610, 2025). "Recent research into the mechanisms by which cancer cells resist ferroptosis has shown that SELENOP, acting as a regulatable selenium source within cancer cells, can be internalized by cells via the receptor LRP8 and subsequently degraded within lysosomes." (PMID 41323827, 2025). "In addition, overexpression of LRP8 could regulate lipid metabolism in BCa cells, causing phospholipid and triglyceride accumulation, which is often associated with the malignant progression of many cancers, such as GC and OC." (PMID 40372166, 2025). "Cancer cells appear to be able to also promote the uptake of selenium by increasing the expression of LRP8." (PMID 39110703, 2024). "Inflammatory monocyte SPON1 acts on LRP8-expressing cancer cells to activate TGF&beta;, which in-turn triggers cancer cell mediated collagen remodeling to promote NSCLC metastases." (PMID 38716730, 2024). "Together, these findings support that SPON1 mediates its effects on cancer metastasis and collagen production through its cognate receptor, LRP8." (PMID 38716730, 2024). "Building upon these previous findings, we identified a mechanistic link by which SPON1+ TIMs signal through LRP8+ cancer cells to activate TGF-β1, resulting in robust cancer cell production of fibrillar collagens." (PMID 38716730, 2024). "Numerous studies have highlighted LRP8's involvement in tumorigenesis across different cancers, with its overexpression often correlating with poor patient prognosis." (PMID 39276062, 2024). "As supported by our TMA analyses, SPON1 TIM expression is coordinated with dual LRP8+ and pSMAD2+ cancer cell expression, which is also correlated with collagen deposition and poor prognosis." (PMID 38716730, 2024). "LRP8 has already emerged as a promising biomarker for the diagnosis and management of carcinomas as well as for predicting their prognosis." (PMID 38495486, 2024). "Selenium, as well as GPX4 levels, accordingly decrease upon knockout of LRP8, the latter being specific for cancer cells." (PMID 36658724, 2023). "Conclusively, a cancer‐specific vulnerability toward ferroptotic cell death can be obtained by knock‐out or pharmacological inhibition of LRP8." (PMID 36658724, 2023). "We show here that selenium/selenocysteine can be obtained by cancer cells via multiple routes: First by the SELENOP/LRP8 axis and second, via the activity of system Xc− (SLC7A11/SLC3A2)." (PMID 37435859, 2023). "Of notice, recent reports have also identified LRP8 as a strong predictor of ferroptosis resistance both in cancer and in neurons." (PMID 37435859, 2023). "Two, how important are the different isoforms of splicing and the complex processing of LRP8 to defining its functions in AD and cancer?" (PMID 36012187, 2022).
cancer (continued). "Specific studies on cancer stem cells and using in vivo xenograft animal models will need to clarify these aspects before LRP8 can be defined as a potential therapeutic marker." (PMID 36012187, 2022). "LRP8 is required for selenium uptake in cells and promotes resistance to ferroptosis in cancer cells due to the expression of GPX4." (PMID 36008942, 2022). "In a scenario in which LRP8 seems to have an oncogenic role in many types of cancer, it remains still elusive the biochemical pathways through which LRP8 exerts such activity." (PMID 36012187, 2022). "Additionally, an overlap in gene signatures between GPX4 and LRP8-overexpressing cancer cells was found." (PMID 41139700, 2026). "The impact of LRP8 expression in cancer and the effects on NK cells are only partially known." (PMID 41139700, 2026). "LRP8 is over-expressed in multiple cancers and is a potential therapeutic target." (PMID 40362181, 2025). "Interestingly, we also found that levels of LRP8 expression on CAFs were comparable with those of our cancer cell lines, and their ability to respond to SPON1 to produce collagens was also comparable." (PMID 38716730, 2024). "Moreover, as a receptor expressed on the cancer cells, LRP8 represents a therapeutic target for blocking TIM-mediated metastases without targeting the TIMs directly." (PMID 38716730, 2024). "Here, by integrating bioinformatic approaches with in vitro and in vivo modeling of the TME, we demonstrate that F-Spondin–expressing (SPON1-expressing) TIMs promote fibrillar collagen production and metastases through a LRP8/TGF-β1 signaling axis in cancer cells." (PMID 38716730, 2024). "In addition, LRP8 promotes the tumorigenesis and progression of several cancers, such as melanoma, gastric cancer, and prostate cancer." (PMID 35246020, 2022). "The present review analyzes the contributions of LDL receptors, specifically of LRP8, in both cancer and neurodegeneration, pointing out that depending on various interactions and peculiar processing, the receptor can contribute to both proliferative and neurodegenerative processes." (PMID 36012187, 2022). "LRP8 is a transmembrane receptor that has been extensively studied in the field of neuroscience, but its role in cancers is still largely unknown." (PMID 30575334, 2019). "LRP5, LRP6, and LRP8 have been shown to play important roles in a broad panel of cancers." (PMID 31031810, 2019). "In addition LRP8 has also gained much attention in its role as one of the coreceptors involved in regulating cancer progression." (PMID 31031810, 2019). "Also, the density of SPON1+ TIMs was modestly correlated with LRP8+ and pSMAD2+ cancer cells (r = 0.27, P < 0.0001), further suggesting an association between SPON1+ TIMs in the tumor and LRP8-associated TGF-β1 activation in cancer cells." (PMID 38716730, 2024). "LRP8 degradation reduces the abundance of several selenoproteins, including GPX4, lowering the cellular threshold for lipid peroxidation and sensitizing cancer cells to ferroptosis." (PMID 42239248, 2026). "NSCLC cells consistently expressed LRP8; however, we observed variable percentages of dual LRP8+ and pSMAD2+ staining, indicating a dynamic activation state of TGF-β1 in the cancer cells." (PMID 38716730, 2024). "The LDL receptor related protein 8 (LRP8) regulates selenium levels and thereby ferroptosis in cancer cells." (PMID 38182558, 2024). "Due to its influence on these pathways, LRP8 silencing inhibited epithelial to mesenchymal transition (EMT) and sensitized cancer cells to chemotherapy." (PMID 39276062, 2024). "Among the receptors in the family, recent studies place low-density lipoprotein receptor-related protein 8 (LRP8) at the center of both neurodegenerative and cancer-related pathways." (PMID 36012187, 2022).
cancer (continued). "The dependency on selenium has been described as a liability for cancer cells and proteins LRP8 and SEPHS2, which are involved in the metabolism of Sec, have been proposed as potential drug targets for cancer." (PMID 36008942, 2022). "In addition to its role in cancer progression, LRP8 (apolipoprotein E receptor 2 [APOER2]) has also been demonstrated to regulate canonical Wnt/β-catenin signaling pathway whereby this pathway plays a role in cell migration and development." (PMID 31031810, 2019). "However, whether LRP8 has a cancer-promoting role in NSCLC via Wnt/β-catenin signaling has not been reported." (PMID 35246020, 2022). "Given that CDC42-GTP promotes F-actin polymerization and filopodia formation, facilitating cancer cell migration and survival at distant metastatic sites, we found that Reelin treatment upregulated GTP-CDC42 in control cells, with no change observed in LRP8 knockdown cells." (PMID 40506610, 2025).
tumor (25 papers, 2014 to 2026). "Meanwhile, we employed mouse xenograft tumor model to replicate the phenomenon that MM cells with high LRP8 expression consume cholesterol, causing low serum cholesterol." (PMID 40199866, 2025). "Analysis of the three cohorts after 14 days of postimplantation showed that both LRP8‐deficient xenograft groups (blue, yellow) showed impaired tumor growth compared with WT controls (red) despite Lip‐1‐mediated ferroptosis inhibition." (PMID 37435859, 2023). "Tumor profile analysis reveals that LRP8 and HDAC4 are associated with immunotherapy outcomes." (PMID 41159493, 2026). "Furthermore, either loss of Spon1 in TIMs or genetic deletion of Lrp8 expression on tumor cells was sufficient to significantly abrogate NSCLC metastases and collagen content within the TME." (PMID 38716730, 2024). "LRP8‐deficient tumors showed a marked decrease in tumor growth and, compared with LRP8 proficient cells, showed a significantly increased overall survival of mice (76d ± vs. 31d ±, defined by reaching termination criteria) with a median survival of 29 days vs. 40 days." (PMID 37435859, 2023). "In BC, LRP8 not only activates tumor cell progression but also reduces the proportion of breast stem cells to suppress chemotherapy resistance and metastasis of BC by regulating the Wnt signaling pathway." (PMID 40372166, 2025). "We manipulated LRP8 expression in tumor cell lines using siRNA or overexpression plasmid transfection." (PMID 40372166, 2025). "Knockdown of LRP8 reduced tumor cell proliferation, migration, invasion, and increased apoptosis while enhancing cisplatin sensitivity." (PMID 40372166, 2025). "More importantly, previous study has demonstrated that LXR/ApoE axis impairs the viability of MDSCs through LRP8, thus facilitating anti-tumor immunity by activating cytotoxic T lymphocytes (CTLs)." (PMID 39972392, 2025). "KAT8 catalyzed the acetylation of SEPP1 at K247/249 and modulated the activity of CD8+ T cells via LRP8 to promote anti-tumor immunity in PC." (PMID 39972392, 2025). "A lower relative GFP fluorescence intensity was observed in zebrafish implanted with LRP8 knockdown cells, suggesting reduced tumor growth." (PMID 40506610, 2025). "Next, the IHC assays were performed to determine the expression of LRP8 in tumor tissues and corresponding adjacent tissues." (PMID 40372166, 2025). "The cisplatin resistance of tumor cells was repressed after knocking down LRP8 and was enhanced by overexpression of LRP8." (PMID 40372166, 2025). "Intriguingly, a chemical agonist LXR-mediated the activation of ApoE secretion devastates MDSC survival by facilitating the binding of ApoE to its receptor LRP8, resulting in a fortified anti-tumor response." (PMID 37124622, 2023). "In summary, LRP8 promoted tumor growth by modulating Wnt/β-catenin signaling in vivo, consistent with the in vitro results." (PMID 35246020, 2022). "Tumor growth was also impaired when apoE-/- B16 cells were injected into lrp8-/- mice, suggesting apoE/LRP8 receptor engagement is important in mediating the apoE protective effect on tumor growth." (PMID 36341364, 2022). "Together with VLDLR and LRP1, LRP8 is also involved in tumor cell growth through its binding to the glycoprotein Proprotein convertase subtilisin/kexin type 9 (PCSK9)." (PMID 36012187, 2022). "We also found that LRP8 is required for anchorage‐independent growth in vitro, and that its depletion in vivo slowed tumor growth in a xenograft model." (PMID 30575334, 2019). "LRP8 depletion significantly decreased tumor growth (adjusted P = 0.003 at all time points after day 11), supporting that LRP8 is a potential candidate treatment target for TNBC." (PMID 30575334, 2019). "Overexpression of LRP8 boosted malignant progression and cisplatin resistance in tumor cells." (PMID 40372166, 2025). "The TCGA results demonstrated that tumor tissues had a noticeable overexpression of LRP8." (PMID 40372166, 2025).
tumor (continued). "Although our findings support that SPON1+ TIMs can upregulate diverse species of collagen production through tumor cell LRP8 expression, we then determined whether CAFs can also produce collagen via a SPON1/LRP8 axis." (PMID 38716730, 2024). "Moreover, LRP8 depletion suppressed cell proliferation, migration, invasion, and epithelial-mesenchymal transition in vitro and impeded tumor growth in vivo." (PMID 35246020, 2022). "Complete deletion of apoE in the tumor cells and in the host was most effective for inhibition of tumor growth, while apoE-/- B16 cells injected into WT mice, or WT B16 cells injected into apoE-/- mice or lrp8-/- mice partially suppressed tumor growth compared to control." (PMID 36341364, 2022). "To determine if knocking out apoE in tumor cells induced immunogenicity, we vaccinated wild type and apoE-/- mice or wild type and lrp8-/- mice with WT B16 or apoE-/- B16 tumor cells and CTLA4 Ab and then collected splenocytes from these vaccinated mice 6 days later." (PMID 36341364, 2022). "Once anti‐LRP8 antibodies become available, evaluations in preclinical studies will be required to determine their effects on tumor growth in TNBC patient‐derived xenograft models, alone and in combination with the standard chemotherapies currently used to treat TNBC in clinical practice." (PMID 30575334, 2019). "As LRP8 was found to have tumorigenic properties in vitro, being required for anchorage‐independent growth, we investigated the effect of LRP8 depletion on tumor growth in a xenograft model, by evaluating the tumorigenic potential of MDA‐MB‐468 cells following their injection into mice." (PMID 30575334, 2019). "The high levels of LRP8 in TNBC and ER−/HER2+ tumors suggested that these tumors might be dependent on LRP8 expression, and that it might be possible to eradicate these tumor cells by targeting LRP8." (PMID 30575334, 2019). "LRP8‐targeting strategies could include antibody approaches based on therapeutic monoclonal antibodies, for example, exploiting its role in tumor progression, or with antibody‐drug conjugates (ADC) to capitalize on its restricted pattern of expression." (PMID 30575334, 2019). "Hence, Lrp8 is actively involved in the regulation of tumor and bone diseases." (PMID 32599940, 2020). "SEPP1 impaired MDSCs viability via LRP8, thereby activating CD8+ T cells to promote anti-tumor immunity in PC." (PMID 39972392, 2025). "This is consistent with a previous report which has demonstrated that LXR/ApoE axis represses MDSCs viability in dependent of LRP8, thereby activating CD8+ T cells and facilitating anti-tumor immunity." (PMID 39972392, 2025). "Using the WT or Lrp8-KO LLC model in WT and Spon1–/– mice, we found significantly decreased tumor burden by IVIS in WT mice with Lrp8-KO tumors, and a significantly diseased metastatic burden in the when both SPON1 and LRP8 are knocked out." (PMID 38716730, 2024). "The other CRC-mucosa-secreted protein activating LRP8 receptor in tumor is Reelin (RELN), a glycoprotein that plays an important role in neuronal migration through the activation of lipoproteins receptors such as LRP8." (PMID 24597571, 2014). "Overexpression of SEPP1 inhibited tumor growth, while this negative effect was reverse by antibody against LRP8." (PMID 39972392, 2025). "Importantly, our work uncovers an intercellular SPON1/LRP8/TGF-β axis that bridges the gap between SPON1+ TIMs and ECM remodeling, while also identifying tumor cells as a key producer of collagen." (PMID 38716730, 2024). "To evaluate whether SPON1 signaling through LRP8 can induce TGF-β1 activation, we evaluated several of our tumor models and spheroids for SMAD2 phosphorylation." (PMID 38716730, 2024). "At present, it is not clear what is the main pathway through which LRP8 can influence tumor proliferation or whether there is a prevalent mechanism in which it is involved." (PMID 36012187, 2022).
tumor (continued). "However, the immune mediated effect was not as apparent in the lrp8-/- mice, as activation of immune pathway and cellular RNA transcripts were not universally increased liked that observed in the complete apoE knock out tumor/mouse model." (PMID 36341364, 2022). "A recent study demonstrated that LRP8 was more strongly expressed in BC without hormone receptor expression (TNBC and HER2 positive) than in luminal tumours (Luminal A and Luminal B)." (PMID 35167614, 2022).